COL5A1 (collagen type V alpha 1 chain)
Diseases named in the same sentence as COL5A1 in open-access papers (continued):
Sharing a sentence is not in itself a finding about the gene and the disease.
diabetes (5 papers, 2018 to 2024). "Besides, diseases associated with COL5A1 gene/protein from the curated CTD Gene-Disease Associations dataset suggested the potential association between COL5A1 and diabetes mellitus with a standardized value of 1.24401." (PMID 36527108, 2022). "Pathological effects of signal peptide mutations have been characterized already in other genes (diseases) such as insulin (diabetes), COL10A1 (Schmid-type metaphyseal chondrodysplasia, MCDS), and COL5A1 (classical Ehlers–Danlos Syndrome, cEDS)." (PMID 29101475, 2018).
mesothelioma (5 papers, 2021 to 2023). A usually malignant and aggressive neoplasm of the mesothelium which is often associated with exposure to asbestos. "To predict possible players, we extracted the list of genes that correlate with the expression of COL1A1 and COL5A1 in adrenocortical carcinoma, kidney renal papillary cell carcinoma, and mesothelioma." (PMID 35739492, 2022). "Interestingly, the addition of COL1A1 and COL5A1 to the CAF Cox model led to a decreased risk score for CAF infiltration in adrenocortical carcinoma, kidney renal papillary cell carcinoma, and mesothelioma." (PMID 35739492, 2022). "Mesothelioma and stomach adenocarcinoma displayed a higher expression profile for the COL1A1, COL5A1, ITGA4, and EMILIN1, in comparison to adrenocortical carcinoma and kidney renal papillary cell carcinoma." (PMID 35739492, 2022). "The Cox analysis illustrated that COL5A1 expression was closely correlated with the OS of patients with adrenocortical carcinoma (ACC), GBM, kidney chromophobe (KICH), KIRC, KIRP, LGG, LUAD, mesothelioma (MESO, pancreatic adenocarcinoma (PAAD), SKCM, STAD, THCA, and uveal melanoma (UVM)." (PMID 35082969, 2022).
serous ovarian cancer (5 papers, 2015 to 2022). "The collagen-remodeling gene, COL5A1, was used in a 10-gene expression signature associated with poor patient survival in high-grade serous ovarian cancer and its expression appears to promote metastasis." (PMID 26039411, 2015). "Interestingly, COL5A1 has been included in a 10-gene signature that is associated with poor survival both in patients with high-grade serous ovarian cancer and renal cell carcinoma." (PMID 31212858, 2019). "This up-regulation of COL5A1 can promote the metastasis and overall survival rate of cases with serous ovarian cancer." (PMID 36523602, 2022).
thyroid cancer (5 papers, 2022 to 2023). "We found five TAD blocks with CoMut genes/events specific to ATC with certain mutation frequency in The Cancer Genome Atlas Thyroid Cancer (TCGA-THCA) cohort, including CoMut pairs MAST/NSUN4, AM129B/TRUB2, COL5A1/PPP1R26, PPP1R26/GPSM1/CCDC183, and PRAC2/DLX4." (PMID 36609218, 2023). "In addition, COL5A1 levels increased with the progression of thyroid cancer and was negatively correlated with the OS of thyroid cancer patients." (PMID 36192735, 2022). "The miR-29b-3p inhibited thyroid cancer invasion and migration by regulating COL1A1 and COL5A1." (PMID 36829181, 2023). "In unpaired samples, the expression levels of COL5A1 and LOXL1 were significantly higher in thyroid cancer than in normal tissues (505 cancer and 59 normal samples), and LYSMD3 levels were significantly lower in thyroid cancer." (PMID 35152572, 2022). "Five survival‐related genes, TMEM63C, COL5A1, LOXL1, ADAMTS2, and LYSMD3 were identified; the expression of COL5A1 and LOXL1 was upregulated in PTC tissues and may be related to OS and PFS of thyroid cancer patients." (PMID 35152572, 2022).
breast tumors (4 papers, 2013 to 2023). "COL3A1, COL5A1 and COL11A1 are fibrillar collagens, which act as “tracks” for metastatic invasion of breast tumors into secondary organs." (PMID 23383328, 2013). "Among the shared upregulated genes in normal breast tissues and breast tumors, the expression of five genes unique to young women aged ≤40 years with BC (i.e., COL1A2, COL5A2, COL5A1, NPY1R, and KIAA1644) significantly affected the OS and RFS of patients with several tumor subtypes." (PMID 35741056, 2022).
COVID-19 (4 papers, 2021 to 2023). A disease caused by infection with severe acute respiratory syndrome coronavirus 2. "All represented terms showed 5 common genes between our ORF-A549 cells and COVID-19 lung biopsies (COL1A1, COL4A3, COL4A4, COL5A1 and COL11A1)." (PMID 37545510, 2023).
esophageal cancer (4 papers, 2022 to 2024). A primary or metastatic malignant neoplasm involving the esophagus. "Although UGT2B15 may influence the expression of COL5A1 and MFAP5, the functional role of these two genes in UGT2B15-induced esophageal cancer cell invasion and metastasis needs to be further clarified by rescue experimental validation." (PMID 38136265, 2023).
glaucoma (4 papers, 2012 to 2022). Increased pressure in the eyeball due to obstruction of the outflow of aqueous humor. "Based on an association study, it was recently reported that the collagen-coding gene COL5A1 (collagen, type V, alpha 1) affects central corneal thickness, which is a glaucoma risk factor." (PMID 22312193, 2012).
lung carcinoma (4 papers, 2019 to 2024). "Both experiments on lung cancer patient tissues and in vitro experiments on lung cancer cells have demonstrated the role of COL5A1 in regulating the mechanical properties of the tumor microenvironment." (PMID 38987529, 2024). "For lung cancer, COL5A1 was highly expressed in patients with recurrence and short survival." (PMID 33178362, 2020). "Our findings revealed that in lung cancer tissues or cells, five transcription factors—FOXA1, CEBPB, CTCF, LMNB1, and POLR2A—concurrently regulate the transcription of COL5A1, MMP1, and SERPINE1." (PMID 39551792, 2024).
meningioma (4 papers, 2020 to 2024). A generally slow growing tumor attached to the dura mater. "In this study, we studied the effect of rs619586 on the signalling pathway of MALAT1/miR‐145/COL5A1 and investigated the association between rs619586 polymorphism and the invasiveness of meningioma." (PMID 32720739, 2020). "In particular, with the presence of rs619586 A>G polymorphism, the expression of MALAT1 and COL5A1 was both reduced, leading to reduced invasiveness of meningioma." (PMID 32720739, 2020). "Consistently, meningioma cells harboring the G genotype of the rs619586 had higher levels of COL5A1." (PMID 34885097, 2021). "For instance, the rs619586 A > G polymorphism of MALAT1 has been shown to affect expression levels of MALAT1 and COL5A1, resulting in lower invasiveness of meningioma." (PMID 34885097, 2021). "And miR‐145 was found to target COL5A1, the interaction between which was shown to be involved in the pathogenesis of invasive meningioma." (PMID 32720739, 2020). "In fact, the deregulation of both miR‐145 and COL5A1 was shown to be involved in the pathogenesis of invasive meningioma." (PMID 32720739, 2020). "Consistent with previous findings, we observed that the meningioma cells carrying the rs619586G genotype showed a higher expression of COL5A1 than those carrying the AA genotype." (PMID 32720739, 2020). "Importantly, the researchers also found that COL5A1 expression is significantly increased in atypical and anaplastic meningiomas." (PMID 38577017, 2024). "Since COL5A1 acted as a key factor affecting the invasiveness of meningioma, inhibited COL5A1 expression could reduce the incidence of invasive meningioma." (PMID 32720739, 2020). "Furthermore, in vitro studies also detected a higher level of COL5A1 mRNA in primary meningioma showing poor miR‐145 expression." (PMID 32720739, 2020). "Also, some recent studies investigated the relationship between the up‐regulation of COL5A1 in human cancers and invasiveness of meningioma." (PMID 32720739, 2020).
pancreatic cancer (4 papers, 2023 to 2025). "We found that Ccn1‐deficient pancreatic cancer cells exhibit reduced expression of collagens, including Col4a1, Col4a2, Col5a1, Col6a1, Col6a2, Col6a3, and Col8a1." (PMID 40287974, 2025). "Upon overexpression of Col5a1 in Ccn1‐deficient pancreatic cancer cells, the expression of Cxcl1 and Cxcl5 were upregulated." (PMID 40287974, 2025). "Similarly, mRNA levels of Col5a1, Col6a1, Col6a2, Col6a3, and Col8a1 were significantly reduced in Ccn1‐deficient pancreatic tumors, while Col4a1 and Col4a2 were unaffected." (PMID 40287974, 2025). "COL5A1 was detected to be highly expressed in multiple cancers, including breast, ovarian and pancreatic cancer; Topoisomerase II alpha (TOP2A) is necessary for the cell cycle and highly expressed during the mitotic process." (PMID 39063036, 2024).
aneurysm (3 papers, 2017 to 2025). Bulging or ballooning in an area of an artery secondary to arterial wall weakening. "In addition, the miR-29 family is involved in aneurysm development by mediating extracellular matrix protein synthesis, including Col1a1, Col3a1, Col5a1, and Eln." (PMID 28164126, 2017). "In murine models of abdominal aortic aneurysms, miR-29b-3p upregulation accelerated aneurysm expansion and increased rupture rates, accompanied by decreased expression of key ECM targets (e.g., Col1a1, Col3a1, Col5a1, and Eln), while inhibition of miR-29b-3p reduced aortic aneurysm progression." (PMID 39767655, 2024).
atherosclerosis (3 papers, 2019 to 2025). A disease characterized by the build-up of fatty material and calcium deposition in the arterial wall resulting in partial or complete occlusion of the arterial lumen. "A previous study showed that the variation of COL5A1 was related to atherosclerosis, which may increase the risk of plaque formation and rupture by affecting the structure and stability of arterial wall." (PMID 41415585, 2025). "These included novel associations of variants at COL5A1 with cerebrovascular disease (P = 4.6 × 10−4), GALNT16 with angina (P = 9.3 × 10−4), MBOAT7 with venous thromboembolism (P = 1.3 × 10−3), GLTPD2 with atherosclerosis (P = 5.3 × 10−4) and SPTLC3 with intracerebral haemorrhage (P = 1.0 × 10−3)." (PMID 31551469, 2019).
Ehlers-Danlos syndrome type 1 (3 papers, 2010 to 2026). "The COL5A1 is an autosomal gene encoding the alpha-1 chain of type V collagen; its pathogenic variants are associated with Ehlers-Danlos syndrome types I and II." (PMID 35911880, 2022). "Finally, mutations in the COL5A1 and COL5A2 genes that encode the chains of type V collagen cause Ehlers-Danlos syndrome types I and II, which are characterized, among other defects, by skin laxity, a feature of the Crtap-/- mice." (PMID 20485499, 2010).
gastric tumors (3 papers, 2022 to 2024). "The hazard ratio of CAF infiltration in COL1A1, COL5A1, ITGA4, EMILIN1, and TSPAN9 signature was even higher, presenting a 36.8 times higher risk of death in gastric tumors with high CAF infiltration." (PMID 35739492, 2022). "Among the signature genes we identified in this study, targeting the COL1A1, COL5A1 and ITGA4 may have a therapeutic potential in gastric tumors with high CAF infiltration." (PMID 35739492, 2022).
osteogenesis imperfecta (3 papers, 2019 to 2024). Osteogenesis imperfecta (OI) comprises a heterogeneous group of genetic disorders characterized by increased bone fragility, low bone mass, and susceptibility to bone fractures with variable severity. "Disruptions in Col5a1 have been implicated in the pathogenesis of osteogenesis imperfecta." (PMID 38656074, 2024). "For example, featured genes such as COL1A1, COL5A1, FN1, and ACTB are involved in invasive breast carcinoma and osteogenesis imperfecta, a heritable bone fragility disorder associated with short stature and abnormalities." (PMID 34858485, 2021).
osteosarcoma (3 papers, 2022 to 2024). A usually aggressive malignant bone-forming mesenchymal neoplasm, predominantly affecting adolescents and young adults. "Comparative expression analysis among the cell lines revealed that COL5A1 was significantly overexpressed in osteosarcoma cell lines (p < 0.05)." (PMID 39712023, 2024). "Notably, among all the cell clusters, COL5A1 + MSCs were increased in osteosarcoma tissues following chemotherapy." (PMID 39033089, 2024). "Currently, there is a lack of research on the role of COL5A1 in osteosarcoma cells; therefore, we selected this gene from our model for further experimental validation." (PMID 39712023, 2024).
prostate carcinoma (3 papers, 2022 to 2024). A carcinoma that arises from epithelial cells of the prostate gland. "The role of COL5A1, which encodes a component of type V collagen, in prostate cancer remains unknown." (PMID 38173042, 2024).
renal carcinoma (3 papers, 2017 to 2019). A carcinoma arising from the epithelium of the renal parenchyma or the renal pelvis. "Gene COL5A1, has shown that its deregulated level was caused by mir-25-3p in renal cancer." (PMID 29299153, 2017).
renal cell carcinoma (3 papers, 2019 to 2024). "High expression of COL5A1 can also accelerate the growth and progression of renal cell carcinoma." (PMID 35530352, 2022).
aortic root dilatation (2 papers, 2020 to 2025). "The classic type of EDS, caused by mutations in the COL5A1 or COL5A2 genes, is characterized by thin, translucent skin, easy bruising, and joint hypermobility, as well as vascular fragility and predisposition to aortic root dilatation and dissection." (PMID 40110250, 2025).
asthma (2 papers, 2017 to 2022). "The increased level of ATG5 was reported to be related to collagen COL5A1 mRNA expression in airways of patients with refractory asthma." (PMID 35820707, 2022). "The findings of positive association between the gene expression of various collagens (i.e., COL5A1 and less significantly COL1A1) and ATG5 supported the speculation that enhanced autophagy is associated with asthma pathogenesis and in particular collagen deposition." (PMID 28424691, 2017).
brittle cornea syndrome (2 papers, 2018 to 2026). Brittle cornea syndrome is a form of Ehlers-Danlos syndrome characterized by a severe ocular manifestations due to extreme corneal thinning and fragility with rupture in the absence of significant trauma, and progression to blindness. "Notably, COL5A1 and COL12A1 mutations underlie classical EDS, TNXB mutations cause a form of EDS with tenascin-X deficiency, and ZNF469 as mentioned is linked to brittle cornea syndrome (sometimes considered an EDS-like condition)." (PMID 41595486, 2026).
cardiomyopathies (2 papers, 2022 to 2025). "The review identified key gene variants affecting athletic performance: endurance (AMPD1, PPARGC1A), power (ACTN3, NOS3), strength (PPARG), and injury susceptibility (COL5A1, MMP3), while also examining inherited conditions like cardiomyopathies (MYH7, MYBPC3)." (PMID 40724525, 2025).
Cirrhosis (2 papers, 2015 to 2019). A chronic disorder of the liver in which liver tissue becomes scarred and is partially replaced by regenerative nodules and fibrotic tissue resulting in loss of liver function. "Patients with cirrhosis showed increased expression in blood of eight genes coding for collagen synthesis COL4A6, COL5A1, COL11A2, COL12A1, COL27A1, COL28A1, COL23A1, COL14A1." (PMID 26317806, 2015).
colon cancer (2 papers, 2023 to 2025). "MiR-18a can affect the onset of colon cancer through the Cdc42/filopodia pathway, and miR-29a can affect the onset of colon cancer by regulating b-3p-COL5A1." (PMID 36755247, 2023).
fibromuscular dysplasia (2 papers, 2023 to 2025). A disorder characterized by fibrous thickening of the arterial wall resulting in narrowing of the arterial lumen. "Further, in one patient with a dissection of the internal carotid artery, we detected a VUS in COL5A1 (p.Pro1436Leu), a gene associated with fibromuscular dysplasia and artery dissection." (PMID 36411388, 2023).
fibrosis (2 papers, 2022 to 2024). the formation of excess fibrous connective tissue in an organ or tissue in a reparative or reactive process. "For example, elevated mRNA expression of COL5A1 and impaired ColV deposition are associated with fibrosis and worsening function of pulmonary tissues in systemic sclerosis." (PMID 36514703, 2022).
Hypertension (2 papers, 2013 to 2023). The presence of chronic increased pressure in the systemic arterial system. "These authors argued that other genetic and environmental factors such as hypertension (in older patients) could have contributed to the COL5A1 already challenged vessel wall." (PMID 23762718, 2013).
metastatic tumor (2 papers, 2020 to 2025). "The COL5A1 mutation was absent in the metastatic tumor population (1MT2), while the CTNNB1 mutation was present exclusively in the metastatic tumor population." (PMID 40004220, 2025).
Myocardial fibrosis (2 papers, 2025). "Meanwhile, the mRNA levels of Col1a1 and Col5a1 (key genes involved in collagen synthesis) also confirmed that CDPs significantly attenuated DOX-induced myocardial fibrosis." (PMID 41462661, 2025). "Besides, the mRNA expression of myocardial fibrosis‐related genes (Col1a1, Col5a1, and Mmp2) was reinstated in mice administered T‐5224." (PMID 40184586, 2025).
myocardial infarction (2 papers, 2022 to 2024). Gross necrosis of the myocardium, as a result of interruption of the blood supply to the area, as in coronary thrombosis. "Experiments in mice show that knocking out Col5a1 increases the scar area after myocardial infarction." (PMID 38921668, 2024). "Another study in mice demonstrated that gene expression of fibroblasts was skewed toward Ki-67, COL1A2, collagen type III alpha 1 chain (COL3A1), collagen type V alpha 1 chain (COL5A1), SPARC, secreted frizzled related protein 2 (SFRP2), and DKK3 following myocardial infarction." (PMID 35548426, 2022).
osteoarthritis (2 papers, 2016 to 2021). A noninflammatory degenerative joint disease occurring chiefly in older persons, characterized by degeneration of the articular cartilage, hypertrophy of bone at the margins and changes in the synovial membrane. "In an animal study dysfunction of COL5A1 was found to generate an abnormal joint phenotype, such as joint laxity and early-onset osteoarthritis." (PMID 27146865, 2016).
Stroke (2 papers, 2023). Sudden impairment of blood flow to a part of the brain due to occlusion or rupture of an artery to the brain. "Apart from pathogenic or likely pathogenic findings, 41 rare VUS in 325 stroke-related candidate genes were detected in 39 probands, including eight novel variants: ABCA1 p.H1223P, ACTA2 p.N298S, COL5A1 p.P930R, FBN1 p.Q514E, FBN1 p.K1052T, GP1BA p.P437*, RNF213 p.N1631Efs*34, and TSC1 p.P397del." (PMID 36580209, 2023).
systemic sclerosis (2 papers, 2022). A chronic disorder, possibly autoimmune, marked by excessive production of collagen which results in hardening and thickening of body tissues. "A previous study revealed that COL5A1 may serve as a biomarker of the early stage of systemic sclerosis based on its autoimmune function." (PMID 35082969, 2022).
triple-negative breast carcinoma (2 papers, 2019 to 2024). An invasive breast carcinoma which is negative for expression of estrogen receptor (ER), progesterone receptor (PR), and human epidermal growth factor receptor 2 (HER2). "COL5A1 is highly expressed in several tumors with high malignancy, particularly in triple-negative breast cancer." (PMID 38918587, 2024).
Vestibular schwannoma (2 papers, 2021 to 2022). A vestibular schwannoma (also known as acoustic neuroma, acoustic neurinoma, or acoustic neurilemoma) is a benign, usually slow-growing tumor that develops from the VIIIth cranial nerve supplying the inner ear. "Low expression of COL4A1 and COL5A1 was associated with recurrence of vestibular schwannoma, while high expression of NPY was associated with recurrence of vestibular schwannoma." (PMID 34691289, 2021).